SYCP2 (synaptonemal complex protein 2)
Diseases named in the same sentence as SYCP2 in open-access papers (continued):
Sharing a sentence is not in itself a finding about the gene and the disease.
Infertility (5 papers, 2022 to 2025). "This study doubles the number of cases of infertile men with heterozygous LOF variants in SYCP2, resulting in an upgraded ClinGen gene–disease clinical validity categorization to strong." (PMID 39202451, 2024). "So far, infertility-related SC gene mutations are limited to four SC genes (SYCP2, SYCP3, C14ORF39, and SYCE1)." (PMID 35342360, 2022). "Through exome sequencing (ES) in a cohort of 627 male patients with diverse infertility phenotypes, three heterozygous SYCP2 frameshift mutations were identified in three azoospermia patients." (PMID 35342360, 2022). "So far, infertility-related mutations have been identified in four SC coding genes, including SYCP2, SYCP3, SYCE1, and C14ORF39." (PMID 35342360, 2022). "Researchers identified exclusive overexpression of SYCP2 from the der allele and revealed three heterozygous SYCP2 frameshift variants in other subjects with cryptozoospermia and azoospermia according to exome sequencing of infertile males." (PMID 36159998, 2022). "In a recent study, three frameshift variants in SYCP2 were identified in men with azoospermia, suggesting that heterozygous loss-of-function variants in SYCP2 might be responsible for the low sperm count and subsequent infertility." (PMID 40432880, 2025). "Four genes with the most observed LoF variants are SYCE1, C14ORF39, SYCP2, and SYCP3, corresponding to the four reported genes with infertility-related mutations." (PMID 35342360, 2022). "In humans, SYCP2 P/LP variants have been reported in a heterozygous state in infertile males but not in women with reproductive failure." (PMID 39545410, 2024). "Second, while variable expressivity regarding the extent of spermatogenesis impairment is a known feature of SYCP2-mediated infertility, the penetrance of the disorder is unknown due to the ascertainment of affected cases." (PMID 39202451, 2024). "In its last comprehensive assessment, three frameshift variants in SYCP2 were identified in men with cryptozoospermia or azoospermia, suggesting that heterozygous loss-of-function (LOF) variants in SYCP2 might be responsible for the low sperm count and subsequent infertility." (PMID 39202451, 2024). "Mice lacking the coiled-coil domain of Sycp2 exhibit spermatocyte apoptosis and male-specific infertility." (PMID 40432880, 2025). "SYCP2 is important for spermatogenesis as mice lacking the coiled-coil domain of Sycp2 exhibit impaired homologous chromosome synapsis, leading to spermatocyte apoptosis and male-specific infertility." (PMID 39202451, 2024).
Azoospermia (3 papers, 2022 to 2025). Absence of any measurable level of sperm,whereby spermatozoa cannot be observed even after centrifugation of the semen pellet. "Similarly, a third case was reported with non-obstructive azoospermia and a homozygous variant in SYCP2, c.2689_2690insT, causing p.(Ala897Valfs*5)." (PMID 39202451, 2024).
female infertility (3 papers, 2024 to 2025). Diminished or absent ability of a female to achieve conception. "While only limited studies have linked SYCP2L to female infertility, its sequence homology with SYCP2 raises the possibility of shared non-canonical functions, such as involvement in the negative regulation of cell death via DNA repair." (PMID 40559621, 2025).
oropharyngeal carcinoma (3 papers, 2015 to 2022). Carcinoma, predominantly squamous cell, arising from the epithelial cells of the oropharynx. "SYCP2 specifically attracts our attention, as it has been shown that deregulation of SYCP2 predicts early stage HPVP oropharyngeal carcinoma and it has been proposed to serve as a biomarker by other authors." (PMID 36142875, 2022).
head and neck cancer (2 papers, 2017 to 2019). A primary or metastatic malignant neoplasm affecting the head and neck. "Mutations in synaptonemal complex protein 2 (SYCP2), a protein involved in meiosis, were associated with lower estimates of Treg cells (-logP = 3, effect size -1.24) and the Treg/CD8 T cell ratio in head and neck cancer." (PMID 28749946, 2017).
ovarian carcinoma (2 papers, 2024 to 2025). A malignant neoplasm originating from the surface ovarian epithelium. "Here, we show that SYCP2, a meiotic protein in the synaptonemal complex, is aberrantly and commonly expressed in breast and ovarian cancers and associated with broad resistance to DDR drugs." (PMID 38383600, 2024). "We show that in breast and ovarian cancer patients, high SYCP2 expression is associated with poor prognosis and resistance to an antibody-conjugated TOP1 inhibitor and platinum, respectively." (PMID 38383600, 2024). "To evaluate the inhibitory effects of ABL1 inhibitors on ovarian cancer cells with elevated SYCP2 expression, we measured expression of SYCP2 in several ovarian cancer cell lines." (PMID 40918650, 2025). "Our investigation further suggests that ovarian cancer cells with elevated SYCP2 expression are highly sensitive to ABL1 inhibitors, such as imatinib and dasatinib, which impair this pathway." (PMID 40918650, 2025). "While our findings suggest that SYCP2-mediated TC-HR operates independently of RAD52 in ovarian cancer, the potential cooperation between these ABL1 substrates—especially under stress conditions—merits further investigation." (PMID 40918650, 2025). "For example, ovarian cancer cells with high SYCP2 expression and R-loop accumulation are more resistant to platinum-based therapies due to their enhanced DNA repair capabilities." (PMID 40918650, 2025). "Here, we treated ovarian cancer cell lines exhibiting varying mRNA levels of SYCP2 with three FDA-approved TKIs targeting ABL1—dasatinib, nilotinib, and imatinib." (PMID 40918650, 2025). "Our recent research has identified Synaptonemal Complex Protein 2 (SYCP2), a meiotic recombination protein, as being upregulated in several cancers, including cervical, breast, and potentially ovarian cancer." (PMID 40918650, 2025). "We demonstrate that tyrosine kinase ABL1 inhibitors inhibit cancer cell proliferation more efficiently in ovarian cancer cell lines with SYCP2 overexpression." (PMID 40918650, 2025). "With an understanding of the role of ABL1-SYCP2 pathway in resistant ovarian cancer cells, we evaluated the translational potential of targeting SYCP2 as a biomarker and therapeutic target." (PMID 40918650, 2025). "In this study, we discovered a novel function of ABL1 kinase in ovarian cancer, where it phosphorylates the overexpressed SYCP2." (PMID 40918650, 2025). "We found that high expression of a meiotic protein, Synaptonemal Complex Protein 2 (SYCP2), is associated with platinum resistance and tyrosine kinase ABL1 inhibitor sensitivity in ovarian cancer." (PMID 40918650, 2025). "To evaluate SYCP2 functionally, we performed SYCP2 knockdown in ovarian cancer cell lines with high SYCP2 expression, including OVCAR8 and SKOV3 (both WT and MUC16+)." (PMID 40918650, 2025). "To confirm the elevated expression of SYCP2 in ovarian cancer, we performed IHC staining on 28 patient samples." (PMID 40918650, 2025). "In breast and ovarian cancer cell lines, high SYCP2 expression correlated with resistance to Cisplatin, a DNA crosslinking agent, and Camptothecin 11 (CPT11, irinotecan), an inhibitor of TOP1." (PMID 38383600, 2024). "Aberrant expression of Synaptonemal complex protein 2 (SYCP2) in breast and ovarian cancers is associated with resistance to drugs targeting the DNA damage response." (PMID 38383600, 2024). "Among all the pathways targeted by drugs, the resistance to drugs targeting the DDR pathway showed the strongest positive correlation with the expression of SYCP2 in several cancer types including breast and ovarian cancers." (PMID 38383600, 2024). "We found that ABL1 inhibitors, such as imatinib and dasatinib, exhibited a negative correlation with platinum resistance, suggesting they could serve as potential treatment options for ovarian cancer cells with overexpressed SYCP2." (PMID 40918650, 2025).
ovarian carcinoma (continued). "Notably, in both Cancer Genomic Atlas (TCGA) and CCLE databases, the meiotic gene SYCP2 is commonly upregulated in breast, cervical, and ovarian cancers and also detected in other cancer types, including lung, head-and-neck, and bladder cancers." (PMID 38383600, 2024). "This retrospective analysis suggests that SYCP2 could serve as a predictive biomarker for the platinum response in ovarian cancer." (PMID 38383600, 2024). "This discovery of SYCP2’s mechanism in DDR provides novel insight that TKIs can impair transcription-associated homologous recombination repair through ABL1-mediated SYCP2 phosphorylation, thus a potential inhibitory effect on platinum-resistant ovarian cancer cells." (PMID 40918650, 2025). "Building upon our previous findings that SYCP2 promotes homologous recombination (HR) by stimulating R-loop formation at sites of DNA damage, we sought to understand the observed correlation between SYCP2 expression levels and sensitivity to ABL1 inhibitors in ovarian cancer cells." (PMID 40918650, 2025). "Moreover, ABL1-mediated Y739 phosphorylation of SYCP2 promotes function of SYCP2 at sites of R-loops by facilitating RAD51 localization and repair, contributing to ovarian cancer cell survival." (PMID 40918650, 2025). "Our study underscores the potential of targeting meiotic recombination proteins, like SYCP2, and the unexplored function of ABL1 at R-loops, as novel therapeutic strategies in overcoming drug resistance and improving outcomes for patients with ovarian cancer." (PMID 40918650, 2025).
breast tumors (1 paper, 2024). "In the TCGA database, SYCP2 expression is significantly higher in breast tumors than in adjacent breast tissue." (PMID 38383600, 2024). "Thus, high SYCP2 expression in breast tumors is a potential marker for poor TOP1i response and poor prognosis in patients." (PMID 38383600, 2024). "Based on the SYCP2 mRNA data from a large number of tumors, we found that the mRNA levels of SYCP2 in breast tumors do not significantly correlate with tumor stages (T1-T4), pathological stages (Stage I-IV), lymph node status (N0-N3), and Her2 levels." (PMID 38383600, 2024).
cardiomyopathy (1 paper, 2024). A disease of the heart muscle or myocardium proper. "Furthermore, genetic studies in mice demonstrated phospholipase Pla2g2a to promote myocardial injury in response to ischemia and oxidative damage, and we selected Sycp2 for its increased expression in cardiomyopathy." (PMID 39285385, 2024).
cervical squamous cell carcinoma (1 paper, 2022). A squamous cell carcinoma arising from the cervical epithelium. "In addition, aberrant expression of SYCP2 which has been considered as a testis-specific human gene was identified in human papillomavirus (HPV)–related tumors, including HPV-positive head and neck squamous cell carcinoma (HNSCC) and cervical squamous cell carcinoma." (PMID 36159998, 2022).
COVID-19 (1 paper, 2022). A disease caused by infection with severe acute respiratory syndrome coronavirus 2. "Seven common DEGs (PPARGC1A, FUBP1, ITGB8, SYCP2, RSAD2, FGF1, and FERMT1) were identified from the GSE164805 dataset of patients with mild COVID-19, and the GSE50395 dataset from APS patients." (PMID 36241659, 2022).
ICF syndrome (1 paper, 2020). "Another study found a decrease in DNA methylation in LCLs of ICF syndrome patients near genes related to germline function (BOLL, SYCP2, LDHAL6A, and NCRNA00221) and an increase in mRNA levels, concordantly with a previous report of germline gene hypomethylation in ICF syndrome patients." (PMID 31963661, 2020).
in situ carcinoma (1 paper, 2015). A malignant epithelial neoplasm which is confined to the epithelial layer without evidence of further tissue invasion. "To evaluate the prognostic accuracy of SYCP2 expression in regions of HPV+ in situ carcinoma, we constructed a receiver operating characteristic (ROC) curve." (PMID 26334652, 2015).
infiltrating ductal carcinoma (1 paper, 2022). "In addition, we also analyzed the prognostic effects of SYCP2 in different subgroups, and the results showed that SYCP2 was a risk factor in the subgroup of T3 stage, N0, M0, and infiltrating ductal carcinoma (HR > 1 and p < 0.05)." (PMID 36159998, 2022). "In stratified analysis, we found that SYCP2 expression remained a powerful forecaster of the prognosis within the subsets, including the T3 stage, N0, M0, and infiltrating ductal carcinoma." (PMID 36159998, 2022).
ovarian tumor (1 paper, 2024). "Moreover, SYCP2 was detected in an ovarian tumor sample from a patient but not in a normal ovary by IHC." (PMID 38383600, 2024).
triple-negative breast carcinoma (1 paper, 2024). An invasive breast carcinoma which is negative for expression of estrogen receptor (ER), progesterone receptor (PR), and human epidermal growth factor receptor 2 (HER2). "We further validated the effects of SYCP2 KD in the triple-negative breast cancer cell line MDA-MB-231." (PMID 38383600, 2024).
tumor (12 papers, 2013 to 2025). "Many of the deregulated transcripts identified in U-E6All cells have been previously identified in HPV-infected cells and tumor samples such as transcripts encoding ribosomal subunits, SYCP2, NUP210 and DICER129–33." (PMID 30976051, 2019). "Instead, DNA hypomethylation of the SYCP2 gene during tumorigenesis is likely an event that enables tumor cells to tolerate genomic instability." (PMID 38383600, 2024). "SYCP2 is overexpressed in tumor samples compared to adjacent benign tissues (P<.01)." (PMID 40918650, 2025). "Because of the constant overexpression of SYCP2, MYB and underexpression of CAV1 in HNSCC, these may be considered potential biomarkers of neoplasms associated to HPV, in addition to p16 and CCND1." (PMID 34830760, 2021). "Screening for circulating tumor DNA from peripheral blood is low invasive and provides fast results, and we suggest screening for HPVP HNSCC using a panel, including RBM24, INHBA, SYCP2, TAFL7, and ZFR2." (PMID 36142875, 2022). "The fact that SYCP2 expression does not correlate with various markers of tumor progression suggests that SYCP2 upregulation is not simply a consequence of tumor progression." (PMID 38383600, 2024). "In particular, SYCP2 expression in cancer might enable cells to tolerate genomic instability, promoting tumorigenesis at the early stage and priming cells to DDR drug resistance during tumor progression." (PMID 38383600, 2024). "Considering that some CT antigens upregulated in HPV-positive cancers may promote genomic instability and that high expression of SYCP2 or STAG3 correlates with improved survival in HSNCC, it is conceivable that aberrant CT antigen expression may contribute to tumor chemo- and radiosensitivity." (PMID 34830845, 2021).
cancer (11 papers, 2011 to 2025). A tumor composed of atypical neoplastic, often pleomorphic cells that invade other tissues. "Our findings that SYCP2 is commonly and aberrantly expressed in cancer cells and associated with resistance to DDR drugs draw attention to the dysregulation of meiotic protein in tumors." (PMID 38383600, 2024). "While few studies have focused on the role of SYCP2 in cancer, others provide further evidence that SYCP2 expression is characteristic of HPV-associated cancers." (PMID 34830845, 2021). "Furthermore, the levels of SYCP2 expression in cancer cells are broadly associated with resistance to DDR drugs." (PMID 38383600, 2024). "On one hand, in cancer cells expressing SYCP2, loss of SYCP2 results in a significant reduction in HR activity, suggesting that SYCP2 may facilitate BRCA1/2-mediated HR." (PMID 38383600, 2024). "Given that HPV16 E6 and E7 can induce DNA damage and promote genomic instability, it is conceivable to hypothesize that SYCP2 upregulation might promote this hallmark of cancer." (PMID 34830845, 2021). "To identify potential treatments to counteract SYCP2-induced platinum resistance, we conducted a drug screening using the Genomics of Drug Sensitivity in Cancer (GDSC) database." (PMID 40918650, 2025). "Consistent with this idea, in cancer cells expressing SYCP2, a faction of the HR activity is dependent on SYCP2, showing that the HR pathway in these cancer cells has become partially SYCP2-dependent." (PMID 38383600, 2024). "Collectively, our data suggest that SYCP2 confers cancer cell resistance to DNA-damaging agents by stimulating R-loop-mediated DSB repair, offering opportunities to improve DDR therapy." (PMID 38383600, 2024). "Together, these results suggest that the upregulation of SYCP2 in cancer preferentially affects the response to DDR-targeted drugs." (PMID 38383600, 2024). "In this study, we show that SYCP2 is commonly and aberrantly expressed in several cancer types, including breast, ovarian and several other cancers." (PMID 38383600, 2024). "Together, these results suggest that, in SYCP2-expressing cancer cells, SYCP2 acts upstream of RAD51 to facilitate RAD51 foci formation upon DNA damage in the HR pathway." (PMID 38383600, 2024). "Aberrant expression of this gene in HPV+ cancers likely contribute to genomic instability and further oncogenic alterations, yet a specific interaction of viral products with SYCP2 is yet to be elucidated." (PMID 30323202, 2018). "It is possible that SYCP2 might cooperate or be mutually exclusive with these meiotic proteins, forming a regulatory network that enables cancer cells to exploit meiotic recombination mechanisms for survival." (PMID 40918650, 2025). "In cancer cells expressing SYCP2, SYCP2 clearly contributes to DSB repair." (PMID 38383600, 2024). "This SYCP2-augemented HR pathway in cancer cells not only allows them to survival intrinsic DNA damage, but also makes them resistant to the DNA damage induced by DDR-targeted drugs, providing a potential therapeutic target and a biomarker for DDR therapy response in cancers." (PMID 38383600, 2024). "In contrast, SYCP2 is aberrantly expressed in cancer cells and augments TC-HR." (PMID 38383600, 2024). "Therefore, our results suggest the meiotic gene SYCP2 is aberrantly expressed in cancer due to DNA hypomethylation." (PMID 38383600, 2024). "Importantly, the aberrant expression of SYCP2 in cancer cells strongly correlates with the resistance to a broad spectrum of DDR drugs, but not drugs targeting other signaling pathways." (PMID 38383600, 2024). "It is known that SYCP2 aberrant expression in HPVP cancers may contribute to the genomic instability induced by high-risk HPVs and subsequent oncogenic change." (PMID 36142875, 2022). "However, in cancer cells suffering oncogenic stress and increased genome instability, the abnormal expression of SYCP2 and perhaps other meiotic proteins may augment TC-HR and allow cancer cell survival." (PMID 38383600, 2024).